COA5 (cytochrome c oxidase assembly factor 5)
Description:
Assembly factor for cytochrome c oxidase (respiratory chain complex IV). Stabilizes an early formation of cytochrome c oxidase assembly factors, until it is displaced by the metallochaperone copper-delivery protein COX17.
Synonyms: C2orf64; PET191; MGC52110; FLJ27524; 6330578E17Rik; CEMCOX3; MC4DN9
Tractability: PROTAC: ubiquitination databases record sites on it; its protein half-life has been measured.
Gene: Protein-coding gene on chromosome 2 (98,598,242 to 98,608,515, reverse strand). Ensembl gene ENSG00000183513.
Subcellular location: Mitochondrion intermembrane space
Subcellular location (Human Protein Atlas): Mitochondria
Pathways (Reactome):
Metabolism: Complex IV assembly
Gene Ontology:
Molecular function: protein binding
Biological process: mitochondrial respiratory chain complex IV assembly
Cellular component: mitochondrion; mitochondrial inner membrane; mitochondrial intermembrane space
Genetic constraint (gnomAD): Loss-of-function variants: 6 observed, 5.31 expected, observed/expected ratio (o/e) 1.13, 90% interval 0.6 to 1.85. That is too few expected variants to judge how well the gene tolerates losing a copy. Missense variants: 66 observed, 58.92 expected, observed/expected ratio (o/e) 1.12, 90% interval 0.92 to 1.38. Synonymous variants: 27 observed, 27.96 expected, observed/expected ratio (o/e) 0.97, 90% interval 0.71 to 1.33.
Gene-disease validity (ClinGen):
ClinGen rates the evidence that COA5 causes each of these diseases.
mitochondrial disease (autosomal recessive): Limited.
Homologues: Orthologues: chimpanzee COA5 (100% identical), guinea pig COA5 (88% identical), macaque COA5 (88% identical), rabbit COA5 (85% identical), pig COA5 (84% identical), mouse Coa5 (82% identical), rat Coa5 (82% identical), tropical clawed frog coa5 (73% identical), zebrafish coa5 (70% identical), Drosophila melanogaster CG13018 (57% identical), Caenorhabditis elegans coa-5 (35% identical).
Diseases named in the same sentence as COA5 in open-access papers:
COA5 is named in the same sentence as 5 diseases in open-access papers, as found by Europe PMC text mining. Sharing a sentence is not in itself a finding about the gene and the disease. The quoted sentences say what the papers report.
cardiomyopathy (1 paper, 2017). A disease of the heart muscle or myocardium proper. "On the basis of these predictions, a pathogenic defect in C2orf64/COA5 was detected in a family with fatal cardiomyopathy and complex IV deficiency." (PMID 28386624, 2017).
mitochondrial disease (1 paper, 2025). "The cytochrome c oxidase assembly factor 5 (COA5) gene (RefSeq: NM_001008215.3), previously denoted as C2orf64, was first reported in humans when a homozygous missense variant (c.157G>C, p.Ala53Pro) in this gene was shown to cause mitochondrial disease." (PMID 39779219, 2025). "Studying a further case of COA5-related mitochondrial disease, the authors delineate an essential role of this protein in the early stage of complex IV assembly." (PMID 39779219, 2025).
COA5 also shares sentences with these, for which no sentence is quoted: encephalomyopathies (1 paper); hypertrophic cardiomyopathy (1); neurological diseases (1).